ABCB1 (ATP binding cassette subfamily B member 1)
Diseases named in the same sentence as ABCB1 in open-access papers (continued):
Sharing a sentence is not in itself a finding about the gene and the disease.
Hypertension (24 papers, 2008 to 2025). The presence of chronic increased pressure in the systemic arterial system. "ABCG2 rs2231142 polymorphism can be used as a predictor of SU-induced thrombocytopenia and hand-foot syndrome in Asian people, while ABCB1 rs1128503 polymorphism can be used as a predictor of SU-induced hypertension." (PMID 40755506, 2025). "The ABCB1 rs1045642 CT + TT (ABCB1—ATP binding cassette subfamily B member) genotype is related to an increasing risk of high blood pressure in patients undergoing treatment with sorafenib (p = 0.037)." (PMID 38397167, 2024). "In this sense, variants in up to four different SNPs in ABCB1 gene have been associated with diabetes mellitus, arterial hypertension and acute nephrotoxicity." (PMID 35214086, 2022). "In arterial hypertension, we found associations of variants in ABCB1 and ABCC2 genes of the recipient with lower risk." (PMID 35214086, 2022). "There was heterogeneity between studies assessing the associations of the ABCB1 rs2032582 polymorphism with sunitinib-induced hypertension and OS (I2 = 80.6%, 63.3%), and the random-effects model was applied to the analysis." (PMID 33762959, 2021). "Compared with the C allele, the ABCB1 rs1128503 T allele was associated with a decreased risk of sunitinib-induced hypertension but worse progression-free survival (PFS) (ES = 0.44, 95% CI = 0.26–0.77, p = 0.004; ES = 1.36, 95% CI = 1.07–1.73, p = 0.011)." (PMID 33762959, 2021). "The ABCB1 rs1128503 T allele is associated with a decreased risk of sunitinib-induced hypertension and worse progression-free survival (PFS)." (PMID 34948113, 2021). "There was no heterogeneity between studies assessing the associations of the ABCB1 rs1128503 polymorphism with sunitinib-induced hypertension (I2 = 0, p > 0.05), and the fixed-effects model was applied to the analysis." (PMID 33762959, 2021). "It has been reported that single-nucleotide polymorphisms in VEGF, VEGFR2, ABCB1 (ATP-binding cassette sub-family B member 1), and eNOS genes predict the rise in blood pressure and/or hypertension in TKI-treated patients." (PMID 33916159, 2021). "Significant correlations between ABCB1 gene polymorphism and increased risk of congenital heart defects, hypertension, stroke, and thrombosis have been previously reported." (PMID 30212560, 2018). "In the present study, another polymorphism located in the exon region of ABCB1 (rs1045642) was found to be significantly associated with hypertension." (PMID 26830973, 2016). "We found that the VEGF rs2010963 CG + GG genotypes had a significantly increased risk of hand-foot syndrome, and the ABCB1 rs1045642 CT + TT genotypes had an increased risk of high blood pressure." (PMID 26830973, 2016). "Therefore, the study of ABCB1 polymorphisms can be employed to personalize drug therapy for arterial hypertension." (PMID 40733143, 2025). "Notably, a specific investigation revealed that the presence of ABCB1 gene polymorphism is closely linked to aberrant lipid metabolism, particularly in the context of hypertension." (PMID 38221931, 2024). "The results showed that compared with the C allele, the ABCB1 rs1128503 T allele was significantly associated with a decreased risk of sunitinib-induced hypertension and worse PFS (ES = 0.44, 95% CI = 0.26–0.77, p = 0.004; ES = 1.36, 95% CI = 1.07–1.73, p = 0.011)." (PMID 33762959, 2021). "Obviously, ABCB1 appears to be functionally associated with the renin-angiotensin aldosterone system (RAAS), one of the main pathogeneses of hypertension." (PMID 36404948, 2022). "On the contrary, gene variants in SLCO1A2, ABCB1 and ABCC2 transporter genes were associated with a lower risk of suffering from type 2 diabetes mellitus, arterial hypertension and acute and chronic nephrotoxicities." (PMID 35214086, 2022).
Hypertension (continued). "Patients carrying the variant genotypes of rs1128503 and rs2032582 in ABCB1 showed an increased clearance of sunitinib and its active metabolite SU12662, consequently leading to lower exposure to sunitinib, reduced hypertension, and decreases in PFS and OS." (PMID 33762959, 2021). "VRP is a calcium channel blocker that was intended for use in the treatment of hypertension and angina for decades, and it is a P-gp inhibitor that reverses MDR caused by ABCB1 in vitro." (PMID 34123833, 2021). "The sensitivity analysis in the meta-analysis of the relationships of the ABCB1 rs2032582 polymorphism with sunitinib-induced hypertension, HFS, PFS, and OS showed that no single study qualitatively altered the pooled ES." (PMID 33762959, 2021). "Genetic variants VEGFR2 rs2239702, ABCB1 rs1045642 and ABCB1 rs2032582 were significantly associated with increased risk of HFS and hypertension; ABCB1 rs1128503 was reported associated with increased risk of hypertension; UGT1A1*6 rs4148323 and UGT1A9 were associated with hypertension." (PMID 28404979, 2017). "In the Seychelles' sample, we measured renal function using the accepted gold standard, inulin clearance, and found that ABCB1 genetic variants are associated with the haemodynamic profile, i.e. GFR, ERPF and RVR in these individuals of African descent with a positive family history of hypertension." (PMID 18518969, 2008). "ABCB1 is a broad-spectrum enzyme that can transport a variety of drugs, including losartan, a selective angiotensin II AT1-receptor antagonist used to treat arterial hypertension and heart failure." (PMID 40733143, 2025). "Polymorphisms including apolipoprotein L1 (APOL1), ATP-Binding Cassette Subfamily B Member 1 (ABCB1), Caveolin 1 (CAV1), and ATP-Binding Cassette Subfamily C Member 2 (ABCC2) have been shown to affect graft survival, hypertension, and calcineurin-induced nephrotoxicity." (PMID 28507980, 2017). "Second, we only chose to study the most important SNPs among AGT1R/ABCB1 genes rather than completely investigate many other SNPs, which might function in the anti-hypertension effect of irbesartan as well." (PMID 36404948, 2022). "Our model that includes non-genetic factors such as age, diabetes and hypertension as well as genetic variants in VKORC1 (rs9923231), CYP2C9 (rs2860905 and 1856908), CES2 (rs4783745), and ABCB1 (rs10276036), explained 60% of the variability in warfarin dose requirements among Puerto Ricans." (PMID 28638342, 2017).
multiple myeloma (24 papers, 2014 to 2026). "In multiple myeloma, overexpression of ABCB1/MDR1 actively pumps the proteasome inhibitor Carfilzomib out of cells via its ATP-dependent efflux pump function, markedly reducing intracellular drug concentration and thereby driving therapeutic resistance." (PMID 40427071, 2025). "Very similar ABCB1 regulation by ALDH1A1-NEK-2 axis was also observed in multiple myeloma, suggesting the significance of high ALDH1A1 regulating ABC transporters’ expression." (PMID 35328460, 2022). "The NGS result showed that 99% of sgRNAs were targeting ABCB1 in round 3-sorted cells, which is the same target with the drug resistant multiple myeloma." (PMID 34977573, 2021). "NFV and LPV restored CFZ activity at therapeutically relevant drug levels and thus represent ready-to-use drugs to be tested in clinical trials to target ABCB1 and to re-sensitize PC to established myeloma drugs, in particular CFZ." (PMID 28676669, 2018). "In the multiple myeloma cell line U266, the ABCB1 promoter was found to be slightly methylated, that of ABCG2 was < LOQ." (PMID 27689338, 2016). "The finding suggested that ALDH1A1 enhanced the drug export activity of myeloma cells in an ABCB1-dependent manner." (PMID 25230277, 2014). "Considering that NEK2 activates AKT and ABCB1 in myeloma, it is possible that ALDH1A1 promotes drug resistance by activating the NEK2-AKT pathway." (PMID 25230277, 2014). "Enforced expression of ALDH1A1 in myeloma cells led to increased activity of the drug efflux pump, ABCB1, and to more vigorous tumor growth in mice." (PMID 25230277, 2014). "Combining both approaches revealed that non-cross-resistant anthracyclines could be identified that might be promising for the treatment of leukemia and multiple myeloma, where ABCB1/MDR1 was a significantly worse prognostic factor." (PMID 40723843, 2025). "ABCB1, also known as MDR1 or P-glycoprotein (P-gp), is one of the well-characterized transporters associated with drug resistance for several types of tumors such as leukemia and colorectal, kidney, and lung multiple myeloma." (PMID 34680470, 2021). "We observed an inverse correlation between the levels of ABCB1 and myeloma cell sensitivity to CFZ." (PMID 28676669, 2018). "Overexpressed ABCB1 is therefore a therapeutic target for CFZ-resistant myeloma." (PMID 28676669, 2018). "The efflux transporters ABCB1 and ABCG2 have been demonstrated to interact with tyrosine kinase inhibitors (TKIs) such as dasatinib, and to reverse drug-resistance in human multidrug-resistant multiple myeloma cells mediated by Src inhibition." (PMID 35164068, 2022). "To dissect the role of ABCB1 overexpression for the activity of standard myeloma drugs we compared the cytotoxic effects of such drugs on AMO-CFZ cells with (clone #1) or without such ABCB1 expression (clone 7)." (PMID 28676669, 2018).
brain tumor (23 papers, 2007 to 2025). "High expression of ABCB1 has previously been associated with chemoresistance and poor outcome in brain tumours including MB, glioma and ependymoma (manuscript in preparation)." (PMID 24887326, 2014). "Furthermore, to investigate the impact of efflux pumps on OMA’s PK profile and accumulation in the brain tumor tissue, we assessed the affinity of this drug for the human P-gp (ABCB1) and BCRP (ABCG2) transporters and the murine variants (Abcb1a and Abcg2) using a Transwell filter transporter assay." (PMID 39770529, 2024). "It is important to note that the cell lines or tumors used in the described studies did not include NSCLC, but they do give an indication about the role of ABCB1/ABCG2 in brain tumors and metastases in general." (PMID 40893689, 2025). "Efflux transporters, particularly P-gp/ABCB1, pose a major barrier to therapeutic drug accumulation in brain tumors by actively extruding a broad spectrum of chemotherapeutic agents from bECs." (PMID 40806198, 2025). "Chemotherapy of primary and secondary brain tumors is often unsuccessful, in part because ABCB1 and ABCG2 at the blood-brain barrier restrict access to a wide range of anticancer drugs to the brain and impair their efficacy." (PMID 36973040, 2023). "ABCB1 is a major ATP-binding cassette transporter of the brain-blood barrier and regulates the trafficking of multiple drugs out of brain tumor cells, including TMZ56,57." (PMID 36477472, 2022). "Pharmacological inhibition of efflux transporters at the BBB has also been proposed for a more effective treatment of brain tumors with anticancer drugs, for which brain distribution is limited by ABCB1/ABCG2-mediated efflux transport." (PMID 31832814, 2019). "ABCB1 expression in endothelial cells also restricts drug access to the brain at the blood brain barrier, limiting the exposure of brain tumours to systemic chemotherapy." (PMID 31311995, 2019). "In brain tumor arising from metastatic breast cancer models, uptake of ABCB1 substrates paclitaxel and doxorubicin was higher than normal brain." (PMID 29186899, 2017). "Consistent with this, human brain tumors of various grades and metastatic brain tumors express ABCB1 to create a BTB." (PMID 29186899, 2017). "High ABCB1 gene expression, which encodes MDR1, is associated with chemo-resistance and poor outcome in many types of brain tumors, including medulloblastomas, gliomas, ependymomas and PAs." (PMID 28137267, 2017). "Despite this, it was found that in pediatric brain tumors, the presence of bisecting GlcNAc in human ABCB1 is correlated with tumor progression, showing a potential relevance of glycomes of ABCB1 as tumor markers." (PMID 27446804, 2016). "By repurposing a hypertension drug, Vardenafil, inhibition of ABCB1-mediated drug resistance was achieved in cell lines established from difficult to treat children's brain tumours." (PMID 26517919, 2015). "For example, constitutive overactivity of the PI3K/Akt pathway induces ABCB1 and ABCG2 expression and their associated proteins’ translocation to the plasma membrane of brain microvasculature endothelial cells, which increases drug resistance of brain tumors." (PMID 36973040, 2023). "In addition to the blood-brain barrier, ABCB1 is also upregulated in tumor tissue samples from brain tumor patients." (PMID 36973040, 2023). "However, to achieve effective ABCB1 inhibition in brain tumor cells, an ABCB1 inhibitor would first need to cross the BBTB." (PMID 31832814, 2019). "We have also previously demonstrated that ABCB1 is expressed in a small subset of brain tumour cells and hypothesised that these cells are selected by current treatments resulting in relapse." (PMID 24887326, 2014). "In addition vardenafil has been shown to selectively increase the blood-brain tumor barrier permeability by inhibiting ABCB1, thereby enhancing the effects of chemotherapeutic drugs in a mouse metastatic brain tumor model." (PMID 21552528, 2011).
brain tumor (continued). "Intriguingly, Vardenafil may not only overcome one particular challenge to brain tumour chemotherapy since it crosses the blood–brain barrier, but its inhibition of ABCB1 may also have a collateral benefit in reducing dissemination and invasion of drug resistant tumour cells." (PMID 26517919, 2015). "Our data suggest that the investigated brain tumors had an intact BBTB, which is impermeable to anticancer drugs, which are dual ABCB1/ABCG2 substrates." (PMID 31832814, 2019). "ABC transporter inhibitors, including ABCB1 and ABCC1 inhibitors, have already been studied in brain tumors in clinical trials." (PMID 31572128, 2019). "This potentially applies to a range of small-molecule kinase inhibitors, which are dual ABCB1/ABCG2 substrates and which are discussed as potential treatment for brain tumors." (PMID 31832814, 2019). "All in all, as human ABCB1 also transports EAI045, it might be possible to enhance the clinical effectiveness of EAI045 in treating (metastatic) brain tumors by inhibiting hABCB1, based on our in vitro and in vivo findings." (PMID 36145346, 2022). "ABCB1 and ABCG2 may also be overexpressed in the membrane of brain tumor cells, which may thus form a second barrier to the effective treatment of brain tumors." (PMID 31832814, 2019). "In this exploratory study, we used PET imaging to assess regional brain delivery of [11C]tariquidar as a small-molecule model ABCB1/ABCG2 substrate in patients with non-contrast-enhancing brain tumors." (PMID 31832814, 2019). "As opposed to these previous studies, we examined in the present study patients with non-contrast enhancing, low- to high-grade brain tumors and used a radiolabeled model ABCB1/ABCG2 substrate instead of a drug which is used for treatment of tumors." (PMID 31832814, 2019). "We found very low brain delivery of the model ABCB1/ABCG2 substrate [11C]tariquidar in patients with non-contrast-enhancing brain tumors without significant differences between tumor and tumor-free brain tissue." (PMID 31832814, 2019). "The data presented in this work show that tariquidar very poorly penetrates the BBTB and may, therefore, not be effective to overcome ABCB1-mediated multidrug resistance of brain tumors." (PMID 31832814, 2019). "The best strategy for an effective treatment of brain tumors may thus be the development of drugs with good passive permeability which are not subject to ABCB1/ABCG2-mediated efflux transport at the BBTB." (PMID 31832814, 2019). "We performed positron emission tomography imaging with the radiolabeled ABCB1 inhibitor [11C]tariquidar, a prototypical ABCB1/ABCG2 substrate, in seven patients with non-contrast -enhancing brain tumors (WHO grades I–III)." (PMID 31832814, 2019).
acute lymphoblastic leukemia (22 papers, 1992 to 2026). Leukemia with an acute onset, characterized by the presence of lymphoblasts in the bone marrow and the peripheral blood. "Further ABCB1 variants of clinical relevance are the missense variants rs2229109 and rs9282564, which are associated with increased risk of relapse of acute lymphoblastic leukemia and paclitaxel toxicity, respectively." (PMID 32206879, 2020). "ABCB1 overexpression occurs in various types of tumors, and high ABCB1 expression is associated with poor prognosis in patients with acute lymphoblastic leukemia." (PMID 26327240, 2015). "In acute lymphoblastic leukemia (ALL), high ABCB1 gene expression has been associated with treatment resistance, which affects patient prognosis." (PMID 30176891, 2018). "A study conducted in two acute lymphoblastic leukemia cell lines, CCRF-HSB-2 (T-ALL) and YAMN90 (B-ALL), found that ABCB1 mRNA increased upon activation of the MAPK/ERK pathway, indicating a potential interaction there; however, it was not established if this regulation is direct or indirect." (PMID 37686513, 2023). "ABCB1 expression has been frequently observed in some human tumors at relapse after chemotherapy, including acute lymphocytic leukemia (ALL), acute nonlymphocytic leukemia (ANLL), breast cancer, and neuroblastoma." (PMID 34572328, 2021). "It seems that LRPPRC may be related to transactivation of MDR genes (ABCB1 and LRP) by invMED sequence in acute lymphoid leukemia." (PMID 22458888, 2012).
diabetes (22 papers, 2010 to 2025). "In a 2012 Korean study of 121 patients with ischemic stroke and 291 controls, ABCB1 polymorphisms were associated with dyslipidemia (rs1128503, p < 0.05), diabetes mellitus (rs3842, p < 0.05), and ischemic stroke (rs4148727, p < 0.05)." (PMID 36144279, 2022). "LR model showed an independent association of ABCB1 2677 G>T/A with post transplant diabetes (OR: 4.83, 95% CI: 1.22–19.03)." (PMID 29621269, 2018). "Logistic regression analysis revealed the independent association of ABCB1 2677 G>T/A with post-transplant diabetes." (PMID 29621269, 2018). "Multifactor dimensionality reduction analysis (MDR) revealed that synergistic interactions between CYP3A5*3 and ABCB1 2677 G>T/A as the determinants of risk for post-transplant diabetes." (PMID 29621269, 2018). "The objective of the current study was to explore the role of ABCB1 and CYP3A5 genetic polymorphisms in predicting the bioavailability of tacrolimus and the risk for post-transplant diabetes." (PMID 29621269, 2018). "Multifactor dimensionality reduction analysis confirmed ABCB1 2677 G>T/A as the major determinant of post-transplant diabetes, which is having strong interaction with CYP3A5*3 polymorphism." (PMID 29621269, 2018). "The gene-gene interactions between ABCB1 and CYP3A5 also influence the risk for post-transplant diabetes." (PMID 29621269, 2018). "We also found that the effects of diabetes on Abcb1 mRNA levels was dependent on both brain regions and Abcb1 species in streptozotocin (STZ)-induced diabetic rats." (PMID 25540622, 2014). "Results pertaining to the influence of diabetes on ABCB1 are variable." (PMID 31269743, 2019). "Furthermore, the presence of variant alleles at ABCB1 2677 and CYP3A5*3 was shown to increase the risk for post-transplant diabetes based on our MDR model, which coincides with the higher bioavailability of tacrolimus in this genotype combination." (PMID 29621269, 2018). "Also, the influence of covariates was evaluated (age, weight, body mass index (BMI), obesity defined as BMI ≥ 30 kg/m2, sex, diabetes mellitus, co-administration of PPI or statins, presence of CYP2C19*2, CYP2C19*17, CYP3A4*1G alleles, and ABCB1 3435 TT genotype)." (PMID 28914344, 2017). "Genetic factors, such as variations in the POR and ABCB1 genes, affect TAC metabolism and may contribute to the development of diabetes mellitus." (PMID 41155647, 2025).